TLR2 (toll like receptor 2)
Diseases named in the same sentence as TLR2 in open-access papers (continued):
Sharing a sentence is not in itself a finding about the gene and the disease.
acanthamoebiasis (5 papers, 2018 to 2020). "It is possible that histopathological changes in the form of inflammatory infiltrates could have been visible in the kidneys of mice in a longer-lasting acanthamoebiasis; statistically significant changes in TLR2 expression were observed only at 24 dpi, the last day of the experiment." (PMID 32958053, 2020). "The first evaluated the effects of Artemisia annua extracts on the expression of TLR2 and TLR4 in the brains of mice with Acanthamoeba infection." (PMID 32679734, 2020). "The second study evaluated the effects of Artemisia annua extracts on TLR2 and TLR4 expression in the lungs of mice with acanthamoebiasis." (PMID 32679734, 2020). "The course of disseminated acanthamoebiasis may be influenced by the host's immunological status, and the observed changes in expression of TLR2 and TLR4 in the host's organs may indicate the role of these receptors in the pathomechanism of acanthamoebiasis." (PMID 31309100, 2019).
acute lung injury (5 papers, 2016 to 2025). A condition of lung damage that is characterized by bilateral pulmonary infiltrates (pulmonary edema) rich in neutrophils, and in the absence of clinical heart failure. "Therefore, SARS-CoV-2-induced acute lung injury (ALI)/ARDS is caused by the downregulation of ACE2, activation of the NLRP3 inflammasome and TLR2/TLR4, and autophagy." (PMID 36851766, 2023). "During acute lung injury (ALI), HMGB1 facilitates the polarization of macrophages toward the M1 phenotype and exacerbates ALI via the NF-κB signaling pathway mediated by TLR2 and TLR4." (PMID 41041277, 2025). "To investigate the in vivo relevance of the PPP1R11/TLR2 pathway, we assayed white blood cell (WBC) pellets for PPP1R11 and TLR2 expression in control and S. aureus-infected patients from our Acute Lung Injury Registry and Biospecimen Repository." (PMID 27805901, 2016).
acute lymphoblastic leukemia (5 papers, 2014 to 2026). Leukemia with an acute onset, characterized by the presence of lymphoblasts in the bone marrow and the peripheral blood. "In another study, the SNPs analysis on patients with newly diagnosed B-cell acute lymphoblastic leukemia (B-ALL) revealed the role of three specific TLR2 and TLR4 genotypes (TLR-2 Arg753Gln, TLR-4 Thr399Ile, and TLR-4 Asp299Gly) that could predict good B-ALL patients outcome." (PMID 37822929, 2023). "In acute lymphoblastic leukemia (ALL) cell lines, TLR1, TLR2, TLR3, TLR4, TLR6 and TLR7 are expressed albeit at variable levels." (PMID 25112836, 2014). "As the most common pediatric malignancy, the B-cell precursor acute lymphoblastic leukemia (BCPALL) expresses detectable alterations in costimulatory molecule expression of TLR2, TLR7, and TLR9, being TLR2 ligands PAM3CSK4 and PGN, the most powerful effect on anti-ALL immune responses." (PMID 37822929, 2023). "For example, Rolf and colleagues demonstrated that stimulation of acute lymphoblastic leukemia (ALL) cell lines and primary ALL samples with the specific TLR1/2 agonist, PAM3CSK4, versus the TLR2/6 agonist, PAM2CSK4, led to distinct activation kinetics of the NF-κB and PI3K pathways." (PMID 27733853, 2016).
AIDS (5 papers, 2012 to 2023). A syndrome resulting from the acquired deficiency of cellular immunity caused by the human immunodeficiency virus (HIV). "In a study of zinc-deficient acquired immune deficiency syndrome (AIDS) patients, zinc supplementation was observed to enhance neutrophilic phagocytosis of opsonized zymosan particles, a Toll-like receptor-2 (TLR2) agonist." (PMID 29295546, 2017). "Thus, certain SNPs in TLR2 may increase the susceptibility of AIDS patients not only to TM, but also to acute hepatitis and other opportunistic coinfections." (PMID 33777838, 2021). "Further, we previously showed significantly increased TLR2 expression in peripheral blood mononuclear cells of Kenyan commercial sex workers with AIDS, which is reduced with HAART treatment." (PMID 22792230, 2012). "The SNPs within the TLR2, TLR4, and TLR9 genes that may contribute to an increased susceptibility of AIDS patients to TM were checked by the time of flight mass spectrometry (TOF/MS) method." (PMID 33777838, 2021). "Among the study subjects, the susceptibility of AIDS patients to TM seems to be independent of the selected TLR2, TLR4, and TLR9 polymorphisms." (PMID 33777838, 2021). "In total, 23 SNPs in the TLR2, TLR4, and TLR9 genes, which may influence the susceptibility of AIDS patients to TM, were checked by the time of flight mass spectrometry (TOF/MS) method among these Han Chinese subjects." (PMID 33777838, 2021). "Studies have found that TLR2 gene expression increased significantly in untreated chronic HIV-1 and AIDS patients’ PBMCs compared to treated and uninfected individuals." (PMID 38140264, 2023). "On the other hand, activation of PRR pathways such as TLR2 and TLR4 may lead to inflammation, promoting HIV replication and accelerating the progression of AIDS, while TLR7 and TLR8 may increase the expression of NF-κB, inhibiting HIV replication and delaying the progression of AIDS in ECs/LTNPs." (PMID 35211115, 2022). "Therefore, it was speculated that derivatives of HIV induced the expression of TLR2 in resting CD4+T cells, thus inducing the acquisition of resting and memory CD4+T cell effector phenotypes and leading to the acceleration of viral replication, immune disorders, and the progression of AIDS." (PMID 35211115, 2022).
anemia (5 papers, 2016 to 2024). A reduction in the number of red blood cells, the amount of hemoglobin, and/or the volume of packed red blood cells. "TC heterozygotes for TLR2 rs3804099 were associated with PTL after correcting for anemia, vaginal bleeding, and history of threatened miscarriage or PTL." (PMID 35877427, 2022). "In the case of TLR2 rs3804099, we found TC heterozygotes to be associated with PTL when adjusted for anemia and vaginal bleeding, observed between 22 and 35 weeks in ongoing pregnancies, as well as for threatened miscarriage or PTL from previous pregnancies." (PMID 35877427, 2022). "In the case of TLR2 rs3804099, the analysis, adjusted by anemia or vaginal bleeding, observed between 22 and 35 weeks of ongoing pregnancy, identified a significant relationship between TC heterozygotes and PTL in over-dominant models (OR 0.63, 95% CI 0.40–0.99; p = 0.046 and 0.044, respectively)." (PMID 35877427, 2022). "We observed that expression of TLR2 in patients with anemia was significantly higher than in patients without anemia (ΔCt TLR2 17.18 ± 14.29 vs 7.10 ± 5.98; p < 0.05)." (PMID 28083607, 2016).
angina (5 papers, 2011 to 2021). "We investigated the expression level of TLR-4 in ACS, as compared with TLR-2 and patients with stable angina." (PMID 25179298, 2016). "By the integration of the DEGs of healthy/MI and unstable angina/MI, the potential targets of Yixinyin for the treatment of MI (ALDH2, C5AR1, CFOS, IL1B, TLR2, TRXR1) have been obtained." (PMID 34799616, 2021). "The present study demonstrated while the expression levels of TLR-4 were higher than those of TLR-2 in all patients, those of TLR-4 were higher in patients with ACS than in stable angina." (PMID 25179298, 2016). "The mRNA expression levels of TLR-4 in the plaque debris were significantly higher than those of TLR2 in all enrolled patients, and they were significantly higher in patients with ACS than with stable angina." (PMID 25179298, 2016).
brain inflammation (5 papers, 2018 to 2024). "We previously found that glutamate release induced by αSf was largely reduced in the presence of an antagonistic antibody against TLR2, a TLR subtype that is probably involved in PD-associated brain inflammation." (PMID 31349736, 2019). "Considering all these results, we explored the role of TLR2 signaling in PGN-induced brain inflammation." (PMID 29719536, 2018). "In accordance with our results, it was described in the literature that MyD88/TLR2 signaling regulated infiltration of the peripheral immune cells populations and microglial expansion in response to the acute brain inflammation." (PMID 29719536, 2018). "H37Rv EVs were found to activate TLR2 signaling and provoke inflammation in RAW264.7 cells and can breach the BBB to initiate brain inflammation." (PMID 39597520, 2024). "TLR2 activates the conduction cascade to amplify the inflammatory response, and TLR4 activates the upregulation of proinflammatory cytokines to trigger brain inflammation." (PMID 35401883, 2022). "Among these, anti-TLR2 and -TLR4 neutralizing antibodies may be considered an interesting approach to block peripheral TLR-mediated inflammation, despite they have no inhibitory effect on brain inflammation." (PMID 36460875, 2023).
breast tumor (5 papers, 2010 to 2025). "In murine models, TLR2 activation has demonstrated the ability to suppress breast tumor growth and metastasis." (PMID 38903515, 2024). "We sought to determine the effect of TLR2 stimulation with infectious bacteria on breast tumor invasiveness and adhesiveness." (PMID 20520770, 2010). "Additionally, in Tlr2–/– MMTV-PyMT mice with spontaneous breast tumors and Tlr2–/– B16F10 tumor-bearing mice, the infiltrations of CD11b+ cDC2s and CD103+ cDC1s in tumors were comparable to that of WT counterparts." (PMID 41291775, 2025). "breast tumor myeloid cells, the expression of 5 TLR genes (TLR1, TLR2, TLR4, TLR7 and TLR8) were detected in >10% of cells and at moderate to high expression levels." (PMID 34956864, 2021).
bronchiolitis (5 papers, 2016 to 2022). Inflammation of the bronchioles characterized by swelling of the bronchioles and mucus accumulation. "The rs1898830 variant in the TLR2 intron gene has previously been significantly associated with severe respiratory syncytial infection and bronchiolitis in neonates." (PMID 35327350, 2022). "We have earlier studied the TLR1rs5743618, TLR2 rs5743708, TLR3 rs3775291, TLR4 rs4986790 and TLR6 rs5743810 polymorphisms, and reported their associations with bronchiolitis and post-bronchiolitis outcomes." (PMID 27498757, 2016). "Furthermore, SNPs in Toll-like receptors (TLRs), including rs4986790*TLR4, rs1898830*TLR2, rs7656411*TLR2, rs352162*TLR9, and rs187084*TLR9 as well as rs2280788*CCL5 were associated with severity of bronchiolitis." (PMID 32375305, 2020). "The joint analyses of the TLR1 rs5743618, TLR2 rs5743708, TLR6 rs5743810 and TLR10 rs4129009 genotype combinations and baseline (z-scores) and hyper-reactivity IOS measurements (Δz-scores) in 97 children hospitalized for bronchiolitis." (PMID 26741133, 2016).
Candidemia (5 papers, 2013 to 2023). A form of invasive candidiasis where species of CANDIDA are present in the blood. "In addition, polymorphisms in the TLR2 gene have been identified as a risk factor for candidemia." (PMID 28289440, 2017).
celiac disease (5 papers, 2008 to 2024). An autoimmune genetic disorder with an unknown pattern of inheritance that primarily affects the digestive tract. "Compared with healthy controls, celiac disease patients had increased TLR4 mRNA expression in peripheral blood, while TLR2 and TLR4 mRNA expression was decreased in duodenal biopsy specimens." (PMID 38475833, 2024). "Increased expression of toll-like receptor 2 (TLR-2) and 4 (TLR-4), claudin 4 (CLD-4), and TNF-α has been shown by different groups in subjects with self-reported gluten intolerance." (PMID 33297984, 2020). "Our results corroborate previously reported results for TLR2 and TLR4 gene expression in IBD and in general for intestinal inflammation such as Celiac Disease and IBS." (PMID 22185629, 2011). "Recent data indicates that TLR2 and TLR4 expression are upregulated in the intestinal mucosa of treated and untreated celiac sprue patients." (PMID 18365016, 2008).
chronic hepatitis C (5 papers, 2010 to 2022). "TLR2 and TLR4 are markedly upregulated in hepatocytes, Kupffer cells, and peripheral monocytes of patients with chronic hepatitis C. TLR2-mediated activation by hepatitis C is linked to the proinflammatory cytokine induction." (PMID 21331379, 2010). "Another study, performed in liver transplant recipients with chronic hepatitis C, treated also at the Mayo Clinic, showed a certain association of TLR2 polymorphism with HCMV load." (PMID 28118851, 2017). "However, in the monocytes of patients with chronic hepatitis C, the expression of TLR2 and TLR4 were up-regulated, and TLR2-mediated pro-inflammatory cytokines, such as TNF- α, are increased." (PMID 35462764, 2022). "Similarly, chronic hepatitis C infection leads to a decrease in expression and functional impairment of TLR2." (PMID 21886831, 2011).
dental caries (5 papers, 2014 to 2024). The decay of a tooth, in which it becomes softened, discolored, and/or porous. "It is also recommended to conduct studies analyzing the role of TLR2 and TLR4 gene–environment interactions in dental caries susceptibility." (PMID 39000094, 2024). "The aim of the present study was to analyze the association of the TLR2 (Toll-like receptor 2 gene) 2258G>A (rs5743708), TLR4 (Toll-like receptor 4 gene) 896A>G (rs4986790), and TLR4 1196C>T (rs4986791) polymorphisms with dental caries in Polish children." (PMID 39000094, 2024). "The aim of the present study was to analyze the association of the TLR2 2258G>A (rs5743708), TLR4 896A>G (rs4986790), and TLR4 1196C>T (rs4986791) polymorphisms with dental caries in Polish children." (PMID 39000094, 2024). "However, further studies conducted in other populations/ethnic groups examining other SNPs are needed to test the consistency of our findings in order to draw definitive, final conclusions regarding the association between TLR2 and TLR4 SNPs and dental caries." (PMID 39000094, 2024). "We also found that the expression of TLR-2 was positively correlated with that of Dectin-1 and may also demonstrate the polymicrobial nature of dental caries." (PMID 36463168, 2022). "We hypothesize that genetic variants of TLR2 and TLR4 that might potentially influence the TLR2 and TLR4 receptor expression and/or function lead to alterations in cariogenic bacteria recognition, binding, and biofilm formation, thus affecting dental caries susceptibility." (PMID 39000094, 2024). "We found a lack of association of alleles, genotypes of TLR2 and TLR4 SNPs, and TLR4 haplotypes with dental caries in Polish children, suggesting that these gene variants do not affect the caries risk (susceptibility)." (PMID 39000094, 2024). "Finally, TLR2 and TLR4 expressions in the dental pulp has been studied using a murine dental caries model." (PMID 30631444, 2018).
dermatophytosis (5 papers, 2017 to 2023). A common fungal infection of the stratum corneum of the skin, hair, or nails by a dermatophyte. "Gene expression by real‐time PCR revealed the increased TLR‐2 and 4 mRNA levels in skin biopsies of cats with dermatophytosis." (PMID 36913145, 2023). "The present study aimed to assess the presence of dermatophyte species in symptomatic cats in a region of Iran and to investigate the expression of TLR‐2 and 4 in cat lesions with dermatophytosis." (PMID 36913145, 2023). "The present study aimed to investigate the expression of TLR‐2 and 4 in cat lesions with dermatophytosis." (PMID 36913145, 2023). "In patients with dermatophytosis, TLR-2 and TLR-4 immunohistochemical staining was observed in lower epidermis from infected skin." (PMID 33343578, 2020). "In situ models showed that TLR2 expression was preserved in the epidermis of patients with localized or disseminated dermatophytosis, while TLR4 was poorly expressed in those patients." (PMID 31824444, 2019). "In a previous report, we provided evidence that TLR2 participates in the host’s epidermis response to dermatophytosis." (PMID 31824444, 2019). "In the present study, we investigated the role of TLR2 during the development of Tm infection in naïve and HH mice to better understand the initial events in deep dermatophytosis." (PMID 28164040, 2017). "To understand the role of TLR2 during the development of murine experimental deep dermatophytosis, we employed TLR2 knockout mice." (PMID 28164040, 2017). "To evaluate the involvement of TLR2 in experimental dermatophytosis, we employed Tm-infected TLR2+/+ and TLR2−/− C57BL/6 mice." (PMID 28164040, 2017). "The in vivo studies suggest a role of TLR-2 in downmodulating inflammation during dermatophytosis." (PMID 33343578, 2020). "Our data support the hypothesis that the absence of TLR2 signals may influence the function of monocytes and could increase the susceptibility to dermatophytosis." (PMID 31824444, 2019). "It is the first time that feline skin biopsies are clinically examined for TLR‐2 and TLR‐4 gene expression in animal dermatophytosis." (PMID 36913145, 2023). "In this study, we aimed to investigate the expression of TLR‐2 and TLR‐4 in feline dermatophytosis lesions and clear the importance of these receptors in host immune response by the recognition of dermatophytes." (PMID 36913145, 2023). "Increased expression of TLR‐2 and TLR‐4 mRNAs in cat skin biopsies suggests that these receptors are involved in the immune response by recognizing dermatophytosis." (PMID 36913145, 2023). "(2015) described that the expression of TLR‐4 (but not of TLR‐2) was decreased in lesions of patients with disseminated dermatophytosis, which indicates the possible mechanism for the chronicity of dermatophytosis." (PMID 36913145, 2023). "In conclusion, we demonstrate that TLR2 diminishes the development of adaptive immune responses during experimental deep dermatophytosis and, in a diabetic scenario, acts to intensify a non-protective inflammatory response." (PMID 28164040, 2017).
emphysema (5 papers, 2013 to 2024). "We have previously shown that CD56+ cells express TLRs and that the percentage of lung NK cells expressing TLR5, TLR6, and TLR2/1 correlated with worsening emphysema as determined by computed tomography quantification." (PMID 25078269, 2014). "In addition, CS-induced emphysema-like alveolar enlargement, apoptosis, and impaired lung function were enhanced in TLR2−/− mice and were decreased in TLR4−/− mice." (PMID 38811459, 2024). "Similarly, NK cells expressing TLR5, TLR6, and TLR2/1 also correlated with worsening emphysema as determined by CT quantification." (PMID 23374856, 2013). "The percentage of lung CD8+ T cells expressing TLR5 and TLR2/1 increased with worsening emphysema." (PMID 23374856, 2013). "We therefore next determined whether the differential role of TLR4 and TLR2 in protecting against the onset of emphysema correlated with alterations in the oxidant/antioxidant ratio in Tlr4−/− and Tlr2−/− mice." (PMID 24205107, 2013). "Here we report a differential requirement for TLR2 and TLR4 in protecting against apoptosis and regulating the oxidative balance in the lung, since Tlr2−/− mice display normal pulmonary oxidative stress and apoptosis levels, and also fail to develop emphysema." (PMID 24205107, 2013). "Collectively, these data demonstrate a non-essential role of TLR2 in emphysema development." (PMID 24205107, 2013). "In addition, while TLR2 has been associated with enhancing airway inflammation and immunity by facilitating the production of cytokines in COPD, the involvement of TLR2 in emphysema development is not known." (PMID 24205107, 2013). "While genetic ablation of the TLR4/MyD88 signaling axis in mice leads to pulmonary cell death and oxidative stress culminating in emphysema, the involvement of Mal, as well as TLR2 which like TLR4 also signals via MyD88 and Mal, in the pathogenesis of emphysema has not been studied." (PMID 24205107, 2013).